Y_RNA (Y RNA )
Gene: Miscellaneous RNA gene on chromosome 1 (156,484,098 to 156,484,210, reverse strand). Ensembl gene ENSG00000206651.
Homologues: Orthologues: chimpanzee Y_RNA (98% identical), macaque Y_RNA (94% identical). Paralogues in human: RNY1 (92% identical), Y_RNA (89% identical), RNY1P11 (88% identical), Y_RNA (88% identical), Y_RNA (87% identical), RNY1P8 (86% identical), Y_RNA (86% identical), Y_RNA (85% identical), Y_RNA (84% identical), RNY1P7 (83% identical), Y_RNA (83% identical), Y_RNA (82% identical), and 99 more.